MMP9 (matrix metallopeptidase 9)
Diseases named in the same sentence as MMP9 in open-access papers (continued):
Sharing a sentence is not in itself a finding about the gene and the disease.
tumor (continued). "The active form of MMP-2 co-localizes with a pro-form of MMP-9 in various types of cancer, being able to activate it, consequently increasing tumor malignancy." (PMID 33308217, 2020). "MMP-2 and MMP-13 were shown to aid the cleavage of the pro domain in pro-MMP-9, which was shown to affect tumor invasion and metastasis by promoting cell migration." (PMID 32466129, 2020). "Co-culturing HepG2 and Huh7-tumor cells with LX2-cells in the transwell assays significantly increased mRNA-expression of the pro-metastatic marker MMP9 in HepG2-cells and MMP1 in HepG2 and Huh7-cells." (PMID 33103995, 2020). "This phenomenon increases the level of p-STAT3, resulting in the increased expression and secretion of MMP-9 and the formation of a positive feedback loop to maintain the invasion and metastasis of tumour cells." (PMID 32209138, 2020). "Similar to this finding, our study confirmed that TAMs that infiltrated into the tumor tissue of tumor-bearing mice are an important source of MMP-9 in the tumor environment." (PMID 32972437, 2020). "In TME, tumor-infiltrating inflammatory cells also help to induce and sustain tumor angiogenesis, and further to facilitate tissue invasion and tumor metastatic spread by releasing some signal molecules such as proinvasive MMP9 and inflammatory chemokines." (PMID 32855630, 2020). "There is considerable accumulating evidence suggesting a role of MMP-2, MMP-3, MMP-9 in promoting tumor cell invasion and infiltration." (PMID 33281914, 2020). "RNA interference (RNAi) targeting MMP3 and/or MMP9 significantly lowered tumor growth and metastasis in the allograft mouse model." (PMID 32260433, 2020). "The degradation of ECM by MMP family members including MMP9 is believed to favour tumour growth, metastasis, invasion and cytoskeletal re-organisation." (PMID 32445177, 2020). "In this study, from the perspective of tumor immunity, we identified MMP9, IGF1, CXCL12 and PGF as prognostic differentially expressed IRGs for the first time." (PMID 32675942, 2020). "MMP9 produced by MDSCs modulates tumour vascularization, hence promotes tumour progression and metastasis." (PMID 32377190, 2020). "It is reported that activated fibroblasts secrete increased levels of ECM-degrading proteases such as MMP2, MMP3, and MMP9, which are very important for tumor invasiveness and are potentially regulated by MYC." (PMID 33081056, 2020). "The results showed that tumor-free cell DNA was able to alter the gene expression of MMP9 and CD44, alter the expression profile of nine miRNAs, and increased the tryptophan consumption and cell migration rates in non-tumor cells." (PMID 33303880, 2020). "Benz markedly inhibited MMP9 expression concomitant with tumor cell migration and invasion and suppressed the dissemination of the tumor cells to the blood circulation and to metastatic secondary tumors in the lungs." (PMID 32102440, 2020). "Matrix metalloprotease-2 (MMP-2) and MMP-9 have been reported to induce tumor cell invasion and metastasis formation." (PMID 32984041, 2020). "Sustained or enhanced MMP9 secretion plays an important role in the pathophysiology of tumor progression." (PMID 33109189, 2020). "Particularly, MMP-2 and MMP-9,also known as “gelatinases”, destroy the barriers enclosing a tumor, including collagen IV of the basement membrane and the extracellular matrix, allowing invasion into the surrounding tissue." (PMID 32718331, 2020). "The results showed that a high expression of CXCL8 in tumour tissues was associated with a high infiltration of TAMs, high expression of VEGF and MMP9, and a low expression of E-cadherin." (PMID 32201645, 2020).
tumor (continued). "Pharmacological and knockout-mouse approaches suggest that targeting MMP-9 and their upstream signaling pathways should yield useful therapeutic targets for brain injury, tumor, and neuroinflammation." (PMID 32505192, 2020). "Increasing studies showed that both the Rho family and MMP family, including Rac1/2/3, CDC42, RhoA, RhoC, MMP2, and MMP9, are highly expressed in a variety of tumor tissues and are directly correlated with tumor migration and invasion." (PMID 33377649, 2020). "Here we show that in response to macrophage-secreted MMP9, tumor cells undergo mesenchymal transition in a PAR1-dependent manner." (PMID 32809114, 2020). "Except for the degeneration of ECM, MMP-2 and MMP-9 also influence the adherence and motility of tumor cells." (PMID 32509341, 2020). "Specifically, MMP-9 and αvβ3 often colocalize at the invasive front of cancers, where MMP-9 drives cellular invasion by degrading the tumor matrix, thus clearing the way for αvβ3-mediated cancer cell migration." (PMID 32630531, 2020). "Of interest, MMP-9 and nitric oxide synthases frequently colocalize at the leading edge of invading tumor cells." (PMID 32630531, 2020). "Our work demonstrated that collagen type I also induces DDR1 mediated synthesis of MMP9 in tumor cells." (PMID 32090682, 2020). "Among them, MMP-2 and MMP-9 are of particular importance for the development of enzyme-responsive anti-tumor drug delivery systems due to their proved correlation with cancer cell invasion and metastasis formation." (PMID 32850662, 2020). "High cytoplasmic MMP9 showed positive association with basal cytokeratin CK17 (p = 0.001) and revealed a low expression in lobular and special type tumours (p = 0.003)." (PMID 32445177, 2020). "MMP-2 (Gelatinase A) together with MMP-9 (Gelatinase-B) are related to tumor invasion and metastasis by their special capacity to degrade type IV collagen in basement membrane, and to induce angiogenesis." (PMID 33114046, 2020). "Among all MMPs, MMP-1, MMP-2, MMP-3, MMP-7, and MMP-9 are involved in almost all stages of tumor growth, angiogenesis, and metastasis." (PMID 32685465, 2020). "In this study, CUR was conjugated with PEI-K14 through CPLGLAG block, which was broken by MMP9 enzymatic hydrolysis in the tumor extracellular matrix." (PMID 32512936, 2020). "MMP-9, in turn, mobilizes endothelial cell precursors from the bone marrow into the circulation, allowing them to reach the tumor." (PMID 32528888, 2020). "AEBR reduces matrix metalloproteinase 2 (MMP2), matrix metalloproteinase 9 (MMP9), and urokinase plasminogen activator (uPA) expression in mouse tumor tissues and also restrains VEGF activity and thus angiogenesis in the tumor tissue." (PMID 32665895, 2020). "S100P secretes matrix metalloproteinase 9 (MMP9) and regulates the invasion of PC cells into the lymphatic endothelial monolayer, thereby promoting tumor cell invasion and metastasis." (PMID 33173782, 2020). "The attracted neutrophils expressed CXCL1 and CXCL8, MMP-2 and MMP-9, thereby inducing tumor angiogenesis and subsequent tumor progression and metastasis." (PMID 32422991, 2020). "Previous studies have identified the critical role of MMP-2 and MMP-9 in tumor invasion and lymph node metastasis of HNSCC." (PMID 32961679, 2020). "Tumor cell-derived EVs stimulate MMP-9, IL-6, and transforming growth factor-β (TGF-β) and induce the secretion of EMMPRIN, which, in the tumor microenvironment, drives immune evasion, invasion, and inflammation that promote tumorigenesis." (PMID 32948029, 2020). "MMP9 can degrade the basement membrane and the matrix surrounding the tumor, help it break through the matrix barrier, and contribute to tumor invasion and metastasis." (PMID 33144895, 2020).
tumor (continued). "The changes in serum concentrations of MMP-9 and tumor responses in NSCLC cases were performed with the same methods as our previous publication." (PMID 32377273, 2020). "MDSCs, TAMs, and neutrophils can produce various proteases, such as matrix metalloproteinase 9 (MMP-9), to promote matrix digestion and remodeling and promote tumor cell migration and extravasation into blood vessels by secreting cytokines." (PMID 31980023, 2020). "IHC analysis showed that immunoreactivity of the invasive marker MMP9 was drastically downregulated in sh-WDR1 tumour tissues." (PMID 32601462, 2020). "This suggests that MMP9 produced by tumor‐infiltrating neutrophils activates TGFβ signaling within the TME." (PMID 31793740, 2020). "An immunohistochemical analysis revealed that the cells secreting MMP-9 were mainly localized in the tumor margin, and most of these cells were macrophages." (PMID 32972437, 2020). "The formation of the invadopodia that promotes the degradation of ECM by the presentation of MMP-14 and secretion of MMP-2 and MMP-9 is a fundamental event during tumor cell invasion." (PMID 33321819, 2020). "As MMP-9 is also heavily involved in tumor cells’ invasion, its role will be discussed in more detail later in this review." (PMID 33081056, 2020). "In this context, MMP-9 protects circulating tumor cells from the lethal actions of natural killer cells or cytotoxic T cells." (PMID 32630531, 2020). "We further demonstrated that TAMs that produced MMP-9 contributed to tumor angiogenesis in tumor tissue and that the reduction in MMP-9 expression in TAMs mediated by infection resulted in the suppression of tumor angiogenesis." (PMID 32972437, 2020). "MMP-9 plays a vital role in the degradation of type IV collagen (the main component of the basement membrane), thereby promoting tumor invasion." (PMID 32698816, 2020). "MMP-2 and MMP-9 play essential roles in metastasis and the expression of these enzymes is most closely related to tumor metastasis and invasion ability." (PMID 33375243, 2020). "Noticeably, MMP-9 counters the anticancer activity of tumor-infiltrating cytotoxic T lymphocytes or natural killer cells." (PMID 32630531, 2020). "In colon cell carcinomas, MMP-9 not only serves as a potential prognostic marker of tumor but also an indicator for tumor metastasis." (PMID 32408577, 2020). "In this work, we show that chemical inhibition of MMPs strongly reduces A375 tumor cell invasive migration and that blockage of DDR1 expression reduces tumor cell synthesis of MMP9, while it also reduces proliferation and migration." (PMID 32090682, 2020). "It should be noted that increased MMP-2 and MMP-9, sometimes expressed by BMDCs, support epithelial-to-mesenchymal transition of tumor cells, allowing them to metastasize." (PMID 33276524, 2020). "MMP-2 and MMP-9 destroy the basement membrane and degrade the extracellular matrix, promoting tumor invasion." (PMID 32102512, 2020). "In cancer pathology, MMP-2 and MMP-9 are mainly implicated in the formation of new blood vessels through angiogenesis; MMP-2 and MMP-9 facilitate the migration of tumor cells to blood vessels by the degradation of basement membrane ECM proteins." (PMID 32522053, 2020). "Another study has been reported that there were correlations between MMP9 expression, stage, depth of tumor invasion, and lymph node involvement which suggested the MMP9 as a marker of GC metastasis." (PMID 32467737, 2020). "The proteinases MMP2 and MMP9 are associated with cancer progression with known roles in degradation and remodelling of the surrounding extracellular matrix (ECM) to facilitate tumour angiogenesis, invasion and metastasis." (PMID 32246008, 2020).
tumor (continued). "MMP-2 and MMP-9 are essential for tumor dissemination, because in addition to playing an important role in the development of invasive processes, they degrade the components of basement membranes, like type IV collagen." (PMID 32813775, 2020). "These TAMs produce molecules that favour tumour biology, such as MMP9 and VEGF that allow for angiogenesis and metastasis." (PMID 32735377, 2020). "Two studies have identified the potential role of SV2B in promoting tumor metastasis, with MMP9, COL3A1 and SV2B being identified as important hub genes that are associated with ECM–receptor interaction." (PMID 32667033, 2020). "The protein expression of N‐cadherin, vimentin, MMP‐2 and MMP‐9 was also analysed in tumour tissues in our established xenograft model." (PMID 32314545, 2020). "MMP9 expression has been shown to promote tumor cell invasion in the lung and recruitment of BMDCs to further induce pro-metastatic ECM remodeling." (PMID 31936750, 2020). "In summary, our findings revealed that downregulation of MMP-2/MMP-9 induces the apoptosis and impairs the viability, migration, and invasion of RB tumor cells, providing a potential MMP target therapy in RB patients." (PMID 32509341, 2020). "The GlioVis database indicated a significant increase in MMP-2, MMP-14, and MMP-9 mRNA in GBM tumor cells compared to normal tissue." (PMID 33182324, 2020). "Further immunohistochemistry analysis of the dissected tumor tissues showed that MT treatment significantly suppressed the protein expression levels of NF-κB, MMP9, MMP2, and p-AKT." (PMID 32117722, 2020). "Differential frequency in the expression of MMP-2 and MMP-9 was observed in epithelial and stromal compartments considering the total of tumor samples: 85 and 56% in epithelium and 65 and 16% in stroma, respectively." (PMID 32718331, 2020). "The upregulation of MMP-9 expression and/or activity occurring in tumor tissues has a major role in the realization of the sequential steps of the metastatic process." (PMID 32630531, 2020). "Among MMPs, MMP-9 (also termed gelatinase B) exerts a variety of activities, most of which favor tumor growth and spread." (PMID 32630531, 2020). "The C-C chemokine receptor type 1 (CCR1) + cells have the characteristic of expressing and secreting matrix metalloproteinase 9 (MMP9), which is involved in tumor invasiveness by promoting tumor–stromal interactions." (PMID 32722068, 2020). "There are at least 23 MMPs and four types of TIMPs expressed in humans, but MMP-2, MMP-9, MMP-14, TIMP-1, and TIMP-2 are often associated with the tumor invasion process." (PMID 32669083, 2020). "After extravasation, MMP-2 and MMP-9 degraded the 100 nm gelatin core NP into smaller 10 nm particles which penetrated deep into tumor tissue via migration through the tumor's ECM." (PMID 33409265, 2020). "The simultaneous HIF-1-induced upregulation of VEGF and increased MMP-9 levels lead to a high concentration of soluble VEGF in the tumour tissue driving angiogenesis and invasiveness." (PMID 33037194, 2020). "The expression of MMP-9 is related to the colonization of tumor cells in bone site and the occurrence of osteolytic lesions." (PMID 32226538, 2020). "The role of MMP-9 in tumor invasion and metastasis has attracted increasing attention and is considered the main proteolytic enzyme in this process." (PMID 32382550, 2020). "In addition, experimental animal models have already indicated a reduced tumour recurrence could be achieved through pharmacological modulation of IRI and properties of tumour cells (such as migration and invasion) with the administration of Rho-associated kinase and MMP-9 inhibitors." (PMID 32806712, 2020). "Western blot analysis of tumour spheres further showed that the expression of EMT‐associated proteins including N‐cadherin, vimentin, MMP‐9 and MMP‐1 was up‐regulated, whereas E‐cadherin expression was down‐regulated." (PMID 32396269, 2020).
tumor (continued). "MMP9 is a component of the angiogenic switch during carcinogenesis, and MMP9-cleaved osteopontin fragments contribute to tumor immune escape by inducing the expansion of myeloid-derived suppressor cells (MDSCs)." (PMID 32988398, 2020). "Doxycycline treatment downregulated the levels of MMP-2, MMP-8, MMP-9 and NF-kB in a dose-dependent manner, which represents another important molecular pattern that restricts tumour cell proliferation, invasion and angiogenesis." (PMID 32377334, 2020). "In various tumor model, the secretion of matrix metallopeptidase 9 (MMP-9) in MDSCs has been reported." (PMID 32508809, 2020). "Several key proteins such as MAP2K1, ITGB4, ITGA6, PTPN6, FMNL1, ANXA1, and MMP9 that modulate cell motility and tumor cell invasion were upregulated in MIBUC." (PMID 32326232, 2020). "MMP-9 was expressed in normal lung tissue, but its expression score was significantly higher in tumor group." (PMID 32944046, 2020). "This action in tumor cells can be explained by the rP21 downregulation of MMP-9 gene expression, while in MCF-10, the MMP-9 expression was not altered." (PMID 33195200, 2020). "On the surface of carcinoma cells which have adhered to the endothelium, the CD44 receptor anchors activated MMP-9 and redistributes it at the invading edge of tumor cells, together with the highly proteolytic MT1-MMP." (PMID 32630531, 2020). "We also studied the role of DDR1 in the expression of MMP9, a key regulator of ECM remodeling implicated in tumor invasion through the collagenous microenvironment and in tumor growth." (PMID 32090682, 2020). "TIMP1 is known to regulate the activity of MMP9, which promotes tumor migration due to extracellular matrix degradation." (PMID 32423054, 2020). "The mechanistic study revealed that RD NPs inhibited the migration and invasion of tumor cells by reducing the expression of NF-κB and MMP-9." (PMID 32847586, 2020). "Both MMP-2 and MMP-9 play important roles in tumor invasion, degrading the matrix and activating latent TGF-β present in the extracellular space." (PMID 32948029, 2020). "In contrast, a cyclic peptide (CILINGITIDE) selectively antagonizing αv integrins did not inhibit glioblastoma progression, despite αvβ3 actively cooperating with MMP-9 to promote tumor cell dissemination." (PMID 32630531, 2020). "We showed that Plasmodium infection significantly inhibited tumor angiogenesis by inhibiting the expression of MMP-9 in TAMs." (PMID 32972437, 2020). "Herein, we found that TENs-activated MSCs expressed higher levels of IL-6, MMP9, TGF-β, and VEGF, which have been previously shown to be associated with the pro-tumor functions of MSCs." (PMID 32903528, 2020). "RWPE-1 cells presented an increased expression of MMP9 in both treatments with tumor isolated cfDNA." (PMID 33303880, 2020). "MiR-145-5p appears to play a key role as a tumor suppressor by targeting N-cadherin and its downstream effector matrix metalloproteinase-9 (MMP9), and it is the most frequently reported downregulated miRNA in BC." (PMID 31615011, 2019). "Previous published work has shown that CD44 and MMP-9 co-localize in tumor cells at the invasive front." (PMID 31579438, 2019). "It has been revealed that MMP2 and MMP9 are involved in regulating tumor cell migration and invasion." (PMID 31007650, 2019). "In malignant melanoma cell lines with high reactive oxygen species (ROS), TAMs increased gene expression of mmp2, mmp9, mmp12, and ctsl proteases known to contribute to tumor invasiveness." (PMID 31737559, 2019). "In patient samples of SSCs, an increase in CD163+ TAMs is associated with enhanced expression of MMP-9 and MMP-11, which promotes angiogenesis and tumor growth." (PMID 31134198, 2019). "Matrix metalloproteinases, such as MMP-2 and MMP-9, are related to the tumor grade and the invasive capacity of glioma." (PMID 31467533, 2019).